MMP2 (matrix metallopeptidase 2)
Diseases named in the same sentence as MMP2 in open-access papers (continued):
Sharing a sentence is not in itself a finding about the gene and the disease.
tumor (continued). "Thus, an inhibitory effect of MMP-2 by SC could be a possible explanation for the favourable outcome associated with a high tumour-specific PIGR expression." (PMID 24694107, 2014). "In particular, tumor cell-associated proteinases such as matrix metalloproteinases MMP2 and MMP9 might play a role in the decline of mechanical barriers represented by extracellular matrices and may be closely related to the incorporation process and importance of EPCs during tumor angiogenesis." (PMID 22496756, 2012). "The fact that MMP-2 is often associated with adjacent normal tissues rather than the tumor cells themselves suggests that neoplastic cells can use MMPs produced by normal cells to facilitate their egress from the tumor mass and potentially their entry into new sites." (PMID 16168111, 2005). "The microRNA-29 (miR-29) family, known to inhibit matrix metalloproteinase-2 (MMP-2), represents a key regulatory axis in tumor invasion." (PMID 42158110, 2026). "In vitro, 2D-primed ADSCs constrained PDAC organoid growth, increased MMP-2 activity, and required direct cell-cell contact to suppress tumor viability." (PMID 41681933, 2026). "Tumor burden, ascites formation, survival, macrophage infiltration, and expression levels of matrix metalloprotease-2 (MMP-2) and transforming growth factor-β (TGF-β) were assessed by histological, immunohistochemical, and molecular analyses." (PMID 42279436, 2026). "Cleavage by MMP-2 in the tumor microenvironment activates the drug, resulting in potent anticancer effects and prolonged circulation half-life." (PMID 41590805, 2026). "During the invasion phase of the primary tumor, TAMs secrete matrix metalloproteinases (MMPs) (e.g., MMP-2, MMP-9, and MMP-13) to degrade the basement membrane and thus establish a pathway for cancer cell invasion." (PMID 41362730, 2026). "For instance, an MMP-2/pH dual-sensitive, hierarchically structured nanoparticle platform was engineered to be size-switchable, dynamically balancing tumor accumulation and deep tissue penetration." (PMID 41362727, 2026). "Matrix metalloproteinase (MMPs) such as MMP-2 and MMP-9 facilitate tumor progression and EMT-associated metastasis directly by degrading the basement membrane components, allowing cancer cells to invade into the surrounding." (PMID 41480643, 2026). "This design optimizes nanoparticle behavior in vivo through laser‐induced expansion and MMP‐2‐induced shrinkage, aiming to enhance accumulation and retention at the tumor site while minimizing side effects on normal tissues." (PMID 41144769, 2025). "MMP2, a matrix metalloproteinase, plays a crucial role in the degradation of the extracellular matrix, facilitating tumor invasion and metastasis." (PMID 39833941, 2025). "This peptide belongs to the chlorotoxin family, characterized by four disulfide bonds that confer structural stability and high binding affinity to tumor-specific ion channels and membrane receptors, such as matrix metalloproteinase-2 (MMP-2)." (PMID 41155199, 2025). "Lastly, the in vitro drug release study identified the tumor microenvironment’s acidic pH (~6.5) as a key trigger for MMP-2-mediated cleavage of the GPLGVRG peptide." (PMID 40732329, 2025). "In future studies, it would be valuable to evaluate the effect of riluzole on MMP2 expression in tumor-bearing mice, particularly in cell lines where riluzole has been shown to inhibit MMP2 expression and activity." (PMID 40391158, 2025). "A recent study has shown that CA’s inhibitory effects on MMP-2 and MMP-9 are linked to its ability to block NF-κB activation, thereby reducing tumor development and spread in hepatocellular carcinoma cancer cells (HCC)." (PMID 40563423, 2025). "MMP2 overexpression is from transcription of HIF-1, and FBN1 buildup can increase the level of HIF-1 and induce MMP2 expression, leading to tumor cell invasion into matrix." (PMID 40865948, 2025).
tumor (continued). "We further monitored the MMP2‐responsive behavior of PreS1‐pHLIP NMs in the MMP2‐enriched tumor microenvironment (TME) using the [Cy5.5+BHQ3] @PreS1‐pHLIP NMs fluorescence probe." (PMID 40091501, 2025). "The anti-EGFR functionalization of the nanoprobe enables it to identify tumor cells with precision and react rapidly to MMP-2 in the local secretory region." (PMID 41002342, 2025). "Tumor-enriched proteases (such as matrix metalloproteinase-2 [MMP2], MMP9, and urokinase plasminogen activator [uPA]3) can cleave the linker and release hemagglutinin (HA)-tagged IL-15 within the TME." (PMID 40532661, 2025). "Previous studies have identified COX-2 as a key mediator of tumor metastasis, primarily through its stimulation of inflammatory mediators that upregulate MMP2 and MMP9 expression, thereby enhancing the metastatic potential of cancer cells." (PMID 41009473, 2025). "Matrix metalloproteinase 2 (MMP2), which facilitates tumor cell migration and invasion by disrupting the basement membrane and degrading the extracellular matrix, also showed reduced expression compared to the control." (PMID 40906092, 2025). "Bisphosphonates also decrease the activation of pro-MMP2 by MT-MMP-1 and thus by decreasing MMP-2 expression, the migration and invasion of tumour cells is significantly decreased." (PMID 41373503, 2025). "This was further demonstrated therapeutically, with a micellar nano system containing calcitriol reducing BC tumor growth and metastasis via the down-regulation of MMP-2 and MMP-9, while at the same time up-regulating the focal adhesion protein paxillin." (PMID 41374952, 2025). "To assess the impact of PMAIP1 knockdown on tumor proliferation and metastasis, we utilized the proliferation marker Ki67 and the metastasis markers MMP2 and MMP9 for further analysis." (PMID 39944827, 2025). "EVs are used by tumor cells as carriers for RNA, DNA, receptors, and proteins, including MMP2, MMP9, high mobility group box 1 (HMGB1), and CD147." (PMID 40345526, 2025). "This highlights the dual role of MMP-2 in promoting tumor progression and modulating immune responses, thereby suggesting it as a critical player in COAD pathogenesis, revealing its potential as a novel therapeutic target." (PMID 40611940, 2025). "Our results indicate that 6-HMDN inhibits FAK phosphorylation and downregulates MMP-2 expression, leading to inhibition of tumor cell migration." (PMID 40563454, 2025). "EC5 displayed high expression levels of genes related to ECM remodeling (COL4A1,COL4A2,HSPG2,MMP2,SPARC),which have been previously implicated in tumor angiogenesis." (PMID 41394809, 2025). "The interaction between BRG1 and the TF specificity protein 1 (SP1) has been shown to be implicated in the expression of the matrix metallopeptidase 2 (MMP2) gene, which is involved in cell migration and tumor invasiveness." (PMID 40065228, 2025). "Elevated MMP-2 and MMP-9 levels in patient tissue samples, serum, or cerebrospinal fluid (CSF) have been associated with advanced tumor grades, an increased risk of recurrence, and lower overall survival." (PMID 40265458, 2025). "This aligns with evidence that high APOC1 expression enhances the secretion of cytokines, such as EGF, PDGF, VEGFA, IL-1, IL-8, TNF-α, MMP-9, MMP-2, and NO, which collectively drive tumor cell proliferation, invasion, and angiogenesis." (PMID 39873475, 2025). "On the other hand, immunohistochemical studies performed in the last decade in a cutaneous context reveal increases in MMP-2 expression in tumour stroma and the parenchyma of invasive squamous cell carcinoma." (PMID 40724562, 2025). "MMP-2 degrades the basement membrane and extracellular matrix and plays an important role in tumor invasion." (PMID 40133252, 2025). "MMP-2 is an important enzyme involved in extracellular matrix remodeling, which facilitates tumor cell invasion and metastasis." (PMID 41155277, 2025).
tumor (continued). "The VEGF-Cand MMP-2 angiogenic factors were studied by observing the nanosystemeffects on endostatin release and tumor necrosis in nude mice witha KYSE-30 cell xenograft." (PMID 40184281, 2025). "MMP-2 is a proteolytic enzyme that degrades extracellular matrix components, facilitating tumor cell invasion and migration." (PMID 40363706, 2025). "In LUAD, especially metastatic tumor cells, the increased expression of MMP-2 and MMP-9 levels is related to basement membrane (BM) and extracellular matrix (ECM) degradation." (PMID 40149594, 2025). "In a xenograft mouse model, treatment with miR-199a-3p-loaded exosomes also reduced peritoneal dissemination and downregulated c-Met, extracellular signal-regulated kinase (ERK) phosphorylation, and matrix metallopeptidase 2 (MMP2) expression in tumor tissues." (PMID 40284522, 2025). "MMP-14, a membrane-type MMP, is also central to tumor invasion, as it activates other MMPs, such as MMP-2, on the cell surface, further enhancing pericellular matrix degradation and enabling cells’ infiltration in GBM." (PMID 40265458, 2025). "MMP-2 is implicated in ECM degradation and contributes to tumor cell growth, differentiation, invasion, metastasis, regulation of tumor angiogenesis, and immune surveillance." (PMID 40894070, 2025). "MMP-2 is also produced by stromal cells and tumor cells to promote processes such as cell migration, invasion, and metastasis." (PMID 41516122, 2025). "NPs functionalized with MMP-2-sensitive peptides can undergo enzyme-mediated degradation, releasing their therapeutic payload precisely in the tumor microenvironment (TME) where MMP-2 activity is elevated." (PMID 41140877, 2025). "Consistent with this notion, our results further revealed that tumor-derived Pvf1 activates Pvr in APCs to increase Mmp2-dependent ECM degradation and APC innervation to upstream neurons, promoting Akh release." (PMID 39924534, 2025). "MMP-2, also known as gelatinase A, has been widely studied for its involvement in tumor microenvironment remodeling." (PMID 41155277, 2025). "HFt-HIS-PASE contains a tumour-selective sequence (MP), responsive to tumour protease MMP-2 and -9 activities, and a shielding polypeptide (PASE) that enhances stability, masks the surface, and increases target specificity." (PMID 41198629, 2025). "Specifically, MMP2 (gelatinase A) and MMP9 (gelatinase B) are associated with tumor spread and cell invasion." (PMID 40391158, 2025). "PEVs have been shown to enhance tumor cell invasion by stimulating MMP-2 synthesis and secretion, as well as by promoting the transcription of MMP-9, VEGF, IL-8, and HGF mRNAs, factors closely associated with lung cancer metastasis." (PMID 41383620, 2025). "Upon tumor colonization, BNPs were selectively released in response to matrix metalloproteinase-2 (MMP-2) activity, ensuring targeted delivery." (PMID 41246256, 2025). "First, while our in vitro experiments provide evidence for the regulatory role of MMP-2 in PD-L1 expression, these findings need to be validated in vivo to ensure their relevance in the complex tumor microenvironment of COAD." (PMID 40611940, 2025). "It has also been shown that this MMP-2 gelatinase is highly expressed during the early stages of squamous carcinogenesis and plays an important role in tumour initiation and growth." (PMID 40724562, 2025). "Classical tumour markers, including MMP2, MMP9, PCNA, and Ki67, had significantly decreased mRNA expression in the siRNA group." (PMID 41284374, 2025). "Its underlying mechanisms involve suppressing MMP-2 expression via the MDM2-mediated degradation pathway, reducing tumor vascular invasion, and enhancing cisplatin chemotherapy sensitivity." (PMID 40115255, 2025). "By breaking down the epithelial-mesenchymal transition (EMT) in the tumor microenvironment, MMP2 facilitates tumor cell invasion into adjacent tissues, promoting metastasis." (PMID 40303286, 2025).
tumor (continued). "The role of MMP-2 in angiogenesis and tumor migration and invasion contributes to the poor prognosis of patients with GBM." (PMID 40791509, 2025). "By conjugating doxorubicin with a trastuzumab epitope and an MMP-2-sensitive peptide linker (Fmoc-KPLGLAGCRGDK), the hydrogel is susceptible to degradation by MMP-2, allowing targeted drug release in the tumor microenvironment." (PMID 40710255, 2025). "The increased levels of MMP-2 and MMP-9 in breast cancer are associated with the development of metastasis, poor survival, and larger tumor size." (PMID 40332096, 2025). "MMPs are zinc-dependent endopeptidases produced by both tumour and non-tumour cells within the tumour microenvironment, with MMP2 and MMP9 classified as gelatinases." (PMID 40259907, 2025). "RAGE activation inhibits hsa-miR-125b-5p, which increases MMP-2 expression and promotes tumor invasion." (PMID 41155277, 2025). "It is well known that in transformed phenotypes, MMP-2 enables tumor invasion and angiogenesis via the degradation of ECM components like collagen, fibronectin, laminin, and elastin." (PMID 40724848, 2025). "In an A375 melanoma model, Lut treatment significantly reduced tumor weight and suppressed MMP-2 and MMP-9 expression, demonstrating its strong anti-cancer potential." (PMID 40563423, 2025). "A fluorescence-based detection of MMP-2, a tumor marker, is challenging to detect at low abundance in the early stages using traditional methods." (PMID 41002342, 2025). "For instance, the POLY-PROTAC nanosystem, activated by MMP-2 enzyme, has demonstrated tumor-site-specific drug release in experiments." (PMID 41488306, 2025). "NanoCRISPR unlocks its self-cascade capability within the matrix metallopeptidase 2-enriched tumor microenvironment, initiating the transcellular penetration." (PMID 41311390, 2025). "Within the MMP family, MMP2, as a gelatinase, plays a pivotal role in tumor invasion, and several groups confirm MMP2’s high expression in MB patient tissues." (PMID 40785845, 2025). "The system was hydrolyzed by MMP-2 into smaller and positively charged CS-siRNA complexes, leading to enhanced tumor penetration, cellular uptake, and lysosomal escape." (PMID 40756358, 2025). "IHC staining analysis revealed that after sesamin treatment for three weeks, the expression of MMP2 decreased in the xenograft tumor tissues." (PMID 40303286, 2025). "Mechanistically, loss of Klk1 promoted extracellular matrix (ECM) remodeling by upregulating Mmp2, Mmp9, Fap, decorin, and β‐catenin, thereby promoting epithelial‐mesenchymal transition and tumor progression." (PMID 40859429, 2025). "MMP-9 and MMP-2 together contribute to the destruction of the extracellular matrix and progressive tumor invasion." (PMID 39066464, 2025). "Due to NF-κB stimulation in tumor cells, MMP-2 and MMP-9 break down ECM type IV collagen during cancer invasion and metastasis." (PMID 40563423, 2025). "In vertebrates, tumor cells can upregulate MMP2 and MMP9 for ECM breakdown of the surrounding tissue in order to facilitate tumor progression and metastasis." (PMID 39977429, 2025). "MMP-2, expressed in both tumor and host cells, was shown to regulate vascular patterning and tumor cell behavior in a dose-dependent manner." (PMID 40265458, 2025). "The MMP gene family, widely implicated in tumor progression, has been well-characterized in NSCLC, particularly MMP2 and MMP9 which play pivotal roles in metastasis and invasion." (PMID 40666104, 2025). "The prognostic significance of tumor size likely reflects its pro-metastatic biology: larger tumors (T2–T4) demonstrate upregulated MMP2/9 expression and enhanced exosome-mediated paracrine signaling, which facilitate lymphatic dissemination." (PMID 40718824, 2025). "The upregulation of MMP-2/9 in the tumor environment removed the PEG shell, exposing folate, enhancing nanoparticle endocytosis by B16 melanoma cells, improving drug targeting, and promoting intracellular chemotherapy uptake." (PMID 40284474, 2025).
tumor (continued). "Our findings reveal that hsa-miR-125b-5p is downregulated upon activation of RAGE by its ligand s100a4, leading to increased MMP-2 expression and enhanced tumor invasion potential." (PMID 41155277, 2025). "The matrix metalloproteinases (MMPs), particularly MMP2, play critical roles in tumor invasion and metastasis, contributing to poor prognosis." (PMID 40303286, 2025). "Given MMP-2’s well-established role in promoting tumor metastasis through extracellular matrix breakdown and angiogenesis, its downregulation by the combination therapy suggests a potential anti-metastatic benefit." (PMID 41401147, 2025). "Due to high expression of matrix metalloproteinase-2 (MMP-2) in the tumor microenvironment, the hydrophilic shell of the nanomicelle was attached to the PVGLIG peptide." (PMID 41140492, 2025). "It is reported that the tumor-derived proteolytically active MMP-2 is an early regulator of metastasis." (PMID 40806510, 2025). "Compared to other metalloproteinases, MMP-2 expression is differentially regulated, thus indicating a unique role in cell–matrix interaction, including tumour invasion." (PMID 40724562, 2025). "Matrix metalloproteinases (MMPs) are a family of zinc-dependent proteases that are considered to be crucial for the invasion, tumor angiogenesis and metastasis of BC, with MMP-2 and MMP-9 being correlated with worse patient prognosis." (PMID 41374952, 2025). "Tumor-associated macrophages (TAMs), particularly of the M2 phenotype, secrete matrix metalloproteinases (MMPs) such as MMP-9 and MMP-2, which degrade collagen and other ECM components, thereby facilitating tumor cell migration and metastasis." (PMID 40787464, 2025). "For instance, in a study, MMP‐2 responsive liposomes were developed to deliver the antifibrotic drug (pirfenidone) to tumor tissue." (PMID 40437741, 2025). "Upon tumor accumulation, MMP-2-mediated scission rapidly disassembles the nanoparticles, enabling spatiotemporally controlled release of BsAbs and dEGCG and thereby enhancing tumor selectivity and local bioactivity." (PMID 41209565, 2025). "During the development of tumor vasculature, berberine reduces the expression of invasive enzymes MMP-2 and μ-PA and down-regulates VEGF in HUVECs." (PMID 40821116, 2025). "Previous studies showed that the lower expression level of E-cadherin and higher expression levels of N-cadherin, β-catenin, and MMP2 were correlated with an increase in tumor cell migration and worse prognosis 18-20." (PMID 40302804, 2025). "These actions involve upregulation of TIMP-1 (tissue inhibitor of metalloproteinase) and MMP-2 (matrix metalloproteinase), both key factors in tumor metastasis." (PMID 40918117, 2025). "The overexpression of MMP-2 reversed the inhibitory effect of Porf-2 on tumor migration in vitro and in vivo." (PMID 40265458, 2025). "During tumor progression, MMP-2/9/14 facilitate tumor cell invasion by breaking down collagen IV in the basement membrane, leading to metastasis." (PMID 39811640, 2025). "Resveratrol limits tumor cell invasion by inhibiting the proteolytic enzymes MMP-2 and MMP-9, which degrade the extracellular matrix and facilitate cancer cell migration." (PMID 40572668, 2025). "According to our results, TA can inhibit numerous molecular targets associated with tumor growth and angiogenesis, including cytokines, COX-2, MMP-2/MMP-9, and VEGF." (PMID 41009634, 2025). "The expression of lncRNA RP11-297P16.4 was negatively correlated to the level of miR-145-5p in NSCLC cells, which sponged miR-145-5p and suppressed tumor cell migration and invasion by targeting matrix metalloproteinase 2 (MMP-2) and MMP-9." (PMID 40149594, 2025). "TA treatment at both doses reduced concentrations of MMP-2 in both ascites macrophages and tumor cells, with a more pronounced effect observed in ascites macrophages (p < 0.001 for both doses) than in tumor cells (p < 0.05 for both doses)." (PMID 41009634, 2025).